OR5D16 (olfactory receptor family 5 subfamily D member 16)
Description:
Odorant receptor.
Synonyms: OR11-154
Tractability: Antibody: UniProt places it where antibodies can reach, with medium confidence; UniProt predicts a signal peptide or a membrane-spanning region; its Gene Ontology location is reachable by antibodies, with medium confidence.
Gene: Protein-coding gene on chromosome 11 (55,838,752 to 55,839,738, forward strand). Ensembl gene ENSG00000205029.
Subcellular location: Cell membrane
Pathways (Reactome):
Sensory Perception: Expression and translocation of olfactory receptors
Gene Ontology:
Molecular function: olfactory receptor activity; G protein-coupled receptor activity
Biological process: G protein-coupled receptor signaling pathway; sensory perception of smell; detection of chemical stimulus involved in sensory perception of smell
Cellular component: plasma membrane; membrane
Genetic constraint (gnomAD): Missense variants: 441 observed, 375.53 expected, observed/expected ratio (o/e) 1.17, 90% interval 1.09 to 1.27. Synonymous variants: 171 observed, 151.47 expected, observed/expected ratio (o/e) 1.13, 90% interval 1 to 1.28.
Homologues: Orthologues: rabbit OR5D16 (81% identical), mouse Or5d16 (78% identical). Paralogues in human: OR5D18 (77% identical), OR5D14 (66% identical), OR5D3 (62% identical), OR5D13 (59% identical), OR5L1 (55% identical), OR5L2 (55% identical), OR5B21 (48% identical), OR5I1 (48% identical), OR5AP2 (48% identical), OR8D1 (48% identical), OR5J2 (47% identical), OR5AR1 (47% identical), and 84 more.
Diseases named in the same sentence as OR5D16 in open-access papers:
OR5D16 is named in the same sentence as 1 disease in open-access papers, as found by Europe PMC text mining. Sharing a sentence is not in itself a finding about the gene and the disease.
OR5D16 shares sentences with these, for which no sentence is quoted: tumor (1 paper).